ALG1 (ALG1 chitobiosyldiphosphodolichol beta-mannosyltransferase)
Description:
Mannosyltransferase that operates in the biosynthetic pathway of dolichol-linked oligosaccharides, the glycan precursors employed in protein asparagine (N)-glycosylation. The assembly of dolichol-linked oligosaccharides begins on the cytosolic side of the endoplasmic reticulum membrane and finishes in its lumen. The sequential addition of sugars to dolichol pyrophosphate produces dolichol-linked oligosaccharides containing fourteen sugars, including two GlcNAcs, nine mannoses and three glucoses. Once assembled, the oligosaccharide is transferred from the lipid to nascent proteins by oligosaccharyltransferases. Catalyzes, on the cytoplasmic face of the endoplasmic reticulum, the addition of the first mannose residues to the dolichol-linked oligosaccharide chain, to produce Man1GlcNAc(2)-PP-dolichol core oligosaccharide. Man1GlcNAc(2)-PP-dolichol is a substrate for ALG2, the following enzyme in the biosynthetic pathway.
Synonyms: MT-1; hMat-1; HMAT1; HMT1; HMT-1; CDG1K; Mat-1
Tractability: Antibody: UniProt predicts a signal peptide or a membrane-spanning region. PROTAC: ubiquitination databases record sites on it; its protein half-life has been measured.
Target class: Enzyme; Transferase
Gene: Protein-coding gene on chromosome 16 (5,033,702 to 5,087,379, forward strand). Ensembl gene ENSG00000033011.
Subcellular location: Endoplasmic reticulum membrane
Subcellular location (Human Protein Atlas): Endoplasmic reticulum; Nucleoli fibrillar center
Pathways (Reactome):
Disease: Defective ALG1 causes CDG-1k
Metabolism of proteins: Biosynthesis of the N-glycan precursor (dolichol lipid-linked oligosaccharide, LLO) and transfer to a nascent protein
Gene Ontology:
Molecular function: chitobiosyldiphosphodolichol beta-mannosyltransferase activity; mannosyltransferase activity; glycosyltransferase activity
Biological process: dolichol-linked oligosaccharide biosynthetic process; protein N-linked glycosylation
Cellular component: membrane; cytoplasmic side of endoplasmic reticulum membrane; endoplasmic reticulum membrane
Genetic constraint (gnomAD): Loss-of-function variants: 65 observed, 56.33 expected, observed/expected ratio (o/e) 1.15, 90% interval 0.94 to 1.42. The synonymous counts are far from expectation, so gnomAD's model fits this gene poorly and the ratio says little. Missense variants: 761 observed, 584.34 expected, observed/expected ratio (o/e) 1.3, 90% interval 1.23 to 1.38. Synonymous variants: 309 observed, 236.83 expected, observed/expected ratio (o/e) 1.3, 90% interval 1.19 to 1.43.
Gene-disease validity (ClinGen):
ClinGen rates the evidence that ALG1 causes each of these diseases.
ALG1-congenital disorder of glycosylation (autosomal recessive): Definitive. A severe form of congenital disorders of N-linked glycosylation characterized by severe developmental and psychomotor delay, muscular hypotonia, intractable early-onset seizures, and microcephaly.
Homologues: Orthologues: chimpanzee ALG1 (99% identical), dog ALG1 (82% identical), rat Alg1 (80% identical), mouse Alg1 (80% identical), macaque ALG1 (74% identical), zebrafish alg1 (59% identical), tropical clawed frog alg1 (51% identical), Drosophila melanogaster Alg1 (43% identical), Caenorhabditis elegans algn-1 (40% identical). Paralogues in human: ALG1L2 (41% identical).
Diseases named in the same sentence as ALG1 in open-access papers:
ALG1 is named in the same sentence as 29 diseases in open-access papers, as found by Europe PMC text mining. Sharing a sentence is not in itself a finding about the gene and the disease. The quoted sentences say what the papers report.
congenital disorder of glycosylation (3 papers, 2022 to 2025). Congenital disorder of glycosylation (CDG) is a fast growing group of inborn errors of metabolism characterized by defective activity of enzymes that participate in glycosylation (modification of proteins and other macromolecules by adding and processing of oligosaccharide side chains). "In particular, NS in infancy or early childhood has been observed in some subtypes of CDG, such as PMM2-CDG (phosphomannomutase 2-congenital disorder of glycosylation) and ALG1-CDG (ALG1-congenital disorder of glycosylation)." (PMID 40868160, 2025). "Patient 7 also carried heterozygous variants in ALG1 and COG5 genes causative of the autosomal recessive disorders: congenital disorder of glycosylation (CDG), type Ik; and CDG, type III, respectively." (PMID 39202394, 2024).
breast carcinoma (2 papers, 2014 to 2021). "Expression levels of ALG1, ALG2, ALG3, ALG8, ALG9, ALG12 and ALG13 were differentially upregulated in radioresistant breast cancer tissues compared with those in radiosensitive tissues, particularly ALG3 with the highest level (4.53-fold change)." (PMID 33931075, 2021).
Ataxia (1 paper, 2022). Ataxia refers to impaired coordination of voluntary muscle movement. "Cerebellar atrophy and ataxia were found only in ALG1‐CDG and PMM2‐CDG, being present in almost all patients in the latter." (PMID 35279850, 2022).
autoimmune disease (1 paper, 2020). A disorder resulting from loss of function or tissue destruction of an organ or multiple organs, arising from humoral or cellular immune responses of the individual to their own tissue constituents. "Besides PMM2-CDG, three reports of autoimmune diseases have been associated with the ALG gene family (eosinophilic esophagitis in an ALG1-CDG patient with a severe phenotype, and psoriasis in an ALG3-CDG and an ALG6-CDG patient)." (PMID 32635232, 2020).
dermatitis (1 paper, 2022). An inflammatory process affecting the skin. "Melanocytic lesions (i.e., acantosis nigricans) were found in ALG1 and SRD5A3 patients, associated with dermatitis in the latter." (PMID 35279850, 2022).
gastroesophageal reflux (1 paper, 2022). "Dysphagia and/or gastroesophageal reflux was present in ALG1‐, ALG6‐, ALG11‐, ALG12‐, DPM1‐, and DOLK‐CDG." (PMID 35279850, 2022).
glioblastoma (1 paper, 2026). The most malignant astrocytic tumor (WHO grade IV). "The pan-cancer analysis revealed that ALG1 is significantly overexpressed in varioustumours, including glioblastoma (GBM), and is linked to poor patient outcomes." (PMID 42002825, 2026).
glioma (1 paper, 2026). A benign or malignant brain and spinal cord tumor that arises from glial cells (astrocytes, oligodendrocytes, ependymal cells). "A prognostic nomogram based on ALG1 levels accurately predicted 1-, 3-, and 5-year survival rates for glioma patients." (PMID 42002825, 2026). "Knocking down ALG1 significantly reduced glioma cell migration and downregulated EMT-related proteins like N-cadherin, β-catenin, and Vimentin." (PMID 42002825, 2026). "This study highlights ALG1 as a key prognostic biomarker and therapeutic target for glioma, promoting malignancy through increased cell migration, EMT modulation, and an altered immunosuppressive microenvironment." (PMID 42002825, 2026). "This study investigates ALG1 expression in glioma and its clinical significance." (PMID 42002825, 2026).
hydrops fetalis (1 paper, 2015). Hydrops fetalis is a severe and challenging fetal condition usually defined as the excessive accumulation of fetal fluid within the fetal extravascular compartments and body cavities that manifests as edema, pleural and pericardial effusion and ascites. "Hydrops fetalis has also been described in PMM2-CDG and ALG1-CDG." (PMID 26066342, 2015).
liver disease (1 paper, 2021). "The authors classified CDG based on liver involvement into two main groups: one with predominant/isolated liver involvement (MPI-CDG, CCDC115-CDG, TMEM199-CDG, ATP6AP1-CDG) and the other associated with liver disease (PMM2-CDG, ALG1-CDG, ALG3-CDG, ALG8-CDG, ALG9-CDG, PGM1-CDG)." (PMID 34291020, 2021).
microcephaly (1 paper, 2017). A congenital or acquired developmental disorder in which the circumference of the head is smaller than normal for the person's age and sex. "This proband has phenotypes consistent with ALG1-CDG (congenital disorder of glycosylation MIM:608540) including severe ID, hypotonia, growth retardation, microcephaly, and seizures, and was included as part of a comprehensive study of ALG1-associated phenotypes." (PMID 28554332, 2017).
ovarian carcinoma (1 paper, 2022). A malignant neoplasm originating from the surface ovarian epithelium. "To gain insight into changes in mannosyltransferases (ALGs), which have been found (ALG1, ALG2, ALG3, ALG9, ALG11 and ALG12) in ovarian cancer, we queried publicly available transcriptomic data, including Gene Expression Omnibus (GEO, GSE18520) and The Cancer Genome Atlas (TCGA) datasets." (PMID 36231102, 2022).
schizophrenia (1 paper, 2018). A major psychotic disorder characterized by abnormalities in the perception or expression of reality. "Genotyping and allele distribution of SNPs on WDR3 and ALG1 genes in schizophrenia and controls from the Japanese population." (PMID 29309433, 2018). "In the present study, we used single nucleotide polymorphisms (SNPs) in the Japanese case-control sample to implement a genetic association study of the WDR3 and ALG1 genes in schizophrenia." (PMID 29309433, 2018). "Furthermore, the chromosome 16p13 region, ALG1 located, was reported to have copy number variations associated with schizophrenia." (PMID 29309433, 2018). "The ALG1 SNPs showed only a statistically-weak correlation, however, two SNPs [A4 (rs3760030) and A7 (rs8045294)] that showed a tendency of association with female schizophrenia were reported as the eQTLs." (PMID 29309433, 2018). "Therefore, we examined 11 SNPs of the human WDR3 gene and 10 SNPs of the human ALG1 gene as the genetic association study of schizophrenia." (PMID 29309433, 2018). "Therefore, WDR3 and ALG1 may also be associated with the susceptibility and/or pathogenesis of schizophrenia." (PMID 29309433, 2018). "This is the first genetic study of the WDR3 and ALG1 genes in schizophrenia to the best of our knowledge." (PMID 29309433, 2018). "Stratification analysis of sex on WDR3 and ALG1 gene in schizophrenia and controls from Japanese population." (PMID 29309433, 2018). "To further elucidate the molecular pathophysiology of schizophrenia, we have evaluated the genetic association of WDR3 and ALG1 in schizophrenia." (PMID 29309433, 2018). "WDR3 SNP W4 (rs319471), W12 (rs10802003) and ALG1 SNP A7 (rs8045294) also displayed a tendency to genotypic association in the female subjects with schizophrenia compared to the female controls, however, it was not significant after multiple testing." (PMID 29309433, 2018). "In the female schizophrenia patients, WDR3 SNP W12 (rs10802003), ALG1 SNP A4 (rs3760030) and A7 (rs8045294) showed significant deviations from the HWE (P = 0.023, 0.026 and 0.024, respectively)." (PMID 29309433, 2018). "The best P-value was the combination of ALG1 SNP A9 (rs7195893) and WDR3 SNP W10 (rs1321666) in the female schizophrenia (P = 0.047), but the TA of this model was less than 0.55 (TA = 0.543)." (PMID 29309433, 2018).
Thrombocytopenia (1 paper, 2025). A reduction in the number of circulating thrombocytes. "Notably, thrombocytopenia has also been described in various other types of CDG, including ALG1-, ALG8-, GALE-, GNE-, MPI-, PMM2-, and B4GALT1-CDG." (PMID 40613041, 2025).
cancer (3 papers, 2022 to 2026). A tumor composed of atypical neoplastic, often pleomorphic cells that invade other tissues. "However, the specific roles of SEC13, ALG1, FAM162A, GALK1, and XYLT2 in cancer remain unclear." (PMID 35963622, 2022). "Additionally, the parental gene ALG1 has not been reported to be involved in cancer." (PMID 35305647, 2022).
autosomal recessive disease (2 papers, 2019 to 2024). Autosomal recessive form of disease. "The regions of heterozygosity involved two genes associated with autosomal-recessive diseases, CDT1, located at 16q24.3, and ALG1, located at 16p13.3." (PMID 31391865, 2019).
tumour (2 papers, 2014 to 2026). "In clinical samples, ALG1 was highly expressed at both mRNA and protein levels, correlating with tumour grade." (PMID 42002825, 2026). "ALG1 overexpression altered tumour microenvironmentsignalling, changing IL10 and CYPA pathways associated with immune suppression." (PMID 42002825, 2026). "Each of the three antibodies similarly differentiated between the COX-2 positive and negative tumours if either ALG1 or ALG3 were used for the evaluation of the expression of the protein within individual lesions (ALG1: 41.5%-48.8%; ALG3: 46.3%-48.8% of the COX-2 positive lesions)." (PMID 25269624, 2014). "ALG1 and ALG3 classified the tumours as COX-2 positive or negative using experimentally determined cut-off thresholds (mean or median value of the score) while ALG2 based on arbitrarily determined cut-off value of 10%." (PMID 25269624, 2014).
infection (1 paper, 2024). The state of being infected such as from the introduction of a foreign agent such as serum, vaccine, antigenic substance or organism. "In the case of alg-1 (χ2 = 81.856, 3 d.f., p < 0.001), infection caused a sharp increase in its expression levels right after heat-shock, which decreased at 8 hphs, at which point control animals displayed significantly higher expression levels of alg-1." (PMID 39137892, 2024).
metabolic disease (1 paper, 2024). A congenital disorder (due to inherited enzyme abnormality) or acquired (due to failure of a metabolically important organ) disorder resulting from an abnormal metabolic process. "ALG1-CDG is a rare, clinically variable metabolic disease, caused by the defect of adding the first mannose (Man) to N-acetylglucosamine (GlcNAc2)-pyrophosphate (PP)-dolichol to the growing oligosaccharide chain, resulting in impaired N-glycosylation of proteins." (PMID 38736633, 2024).
neurodevelopmental disorder (1 paper, 2021). A behavioral and cognitive disorder with onset during the developmental period that involves impaired or aberrant development of intellectual, motor, or social functions. "In the case of CDG with the primary neurological phenotype (neurodevelopmental disorders), including ALG1-CDG, ALG3-CDG, ALG13-CDG, and DPAGT1-CDG, liver is affected in a minority of patients." (PMID 34291020, 2021).
ALG1 also shares sentences with these, for which no sentence is quoted: Cerebellar atrophy (1 paper); cutis laxa (1); dilated cardiomyopathy (1); eosinophilic esophagitis (1); Intellectual disability (1); psoriasis (1); renal failure (1); sensorineural hearing loss (1); viral infections (1).